GPX4 (glutathione peroxidase 4)
Diseases named in the same sentence as GPX4 in open-access papers (continued):
Sharing a sentence is not in itself a finding about the gene and the disease.
melanoma (continued). "GPX2 and GPX4 have been demonstrated to play a role in the resistance of melanoma to therapies." (PMID 35326683, 2022). "Similarly, previously chemotherapy-insensitive xenograft melanomas in mice exhibited sensitivity to the chemotherapeutic agents dabrafenib and trametinib after Gpx4 was knocked out." (PMID 35883577, 2022). "Whether the Arg2-Akt-GPX4 axis modulates sorafenib-induced ferroptosis in human melanoma cells requires further validation." (PMID 36604146, 2022). "Breast, melanoma, lung, and ovarian cancer treated with different therapies develop GPX4 dependence and ferroptosis hypersensitivity, which are metabolic hallmarks of persister cells, an early, drug-induced state that is associated with acquired therapy resistance and tumor relapse." (PMID 32577235, 2020). "ADT and Enz-induced sensitivity to GPX4 inhibition of PCa cells was reminiscent of lapatinib- and vemurafenib-induced drug tolerance and emergence of “persister cells” in melanoma, breast, lung, and ovarian cancer and therapy-resistance-associated high-mesenchymal state cancer cells." (PMID 32577235, 2020). "Therefore, SLC7A11/GSH/GPX4 is an essential axis in melanoma ferroptosis." (PMID 37373523, 2023). "The same study demonstrated that GPX4 inhibition could then reduce the viability of a human-derived, erlotinib-insensitive prostate cancer organoid with high ZEB1 expression and that GPX4 deficiency halted the growth of a melanoma xenograft in mice." (PMID 35883577, 2022). "In addition, inactivation of GPX4 and subsequent induction of ferroptosis has been shown to selectively ablate drug tolerant cell populations in preclinical models of melanoma, as well as other cancer types, whilst having little effect on treatment naïve cell populations." (PMID 34830962, 2021). "GNA triggered ferroptosis in melanoma cells by decreasing lncRNA nuclear-enriched abundant transcript 1 (NEAT1) and downregulating levels of SLC7A11/glutathione peroxidase 4 (GPX4)." (PMID 40900835, 2025). "Melanoma cells were shown to undergo ferroptosis through the Keap1-NRF2-heme oxygenase 1 (Hmox1) pathway when Gel@WA-cRGD inhibited GSH and GPX4 expression." (PMID 38853203, 2024). "Another study reported ferroptosis inducers (FINs) such as sorafenib, RSL3, sulfasalazine, and erastin, synergistically increased the effect of radiotherapy in various cancers, including melanoma, by reducing SLC7A11 expression or inhibiting GPX4." (PMID 37996827, 2023). "While lnc NEAT1 is known to be upregulated in melanoma, downregulation of lnc NEAT1 induces ferroptosis through weakening of the direct binding to SLC7A11, indirectly resulting in inhibiting GPX4 and inducing ferroptosis." (PMID 37795022, 2023). "GPX4 deletion reduces the ability of 27HCR and B16F10 melanoma cells to metastasis in comparison to melanoma cells of the wild type." (PMID 37598126, 2023). "Expressions of GPX2, GPX4, GSR, and G6PD have been found to be elevated in melanomas and other cancers." (PMID 35326683, 2022). "In summary, our research demonstrated that nobiletin triggered ferroptosis in human melanoma cells, as well as increased lipid peroxidation, ROS accumulation, GSH depletion, GPX4 inactivation, and iron accumulation." (PMID 35350242, 2022). "Melanoma cells with lower levels of ciRS-7 are more sensitive to multiple MAPK pathway inhibitors and GPX4 inhibitors." (PMID 32171304, 2020). "In a prospective cohort of LUAD and melanoma patients, CTCs co-expressing CBX3 and GPX4 were selectively elevated in the blood samples of metastatic cases compared to the non-metastatic group, highlighting the clinical association between ferroptosis-resistant CTCs and metastatic progression." (PMID 41540451, 2026).
melanoma (continued). "Targeting Glutathione peroxidase 4 (GPX4), a key enzyme that protects cells against oxidative damage, with deoxyelephantopin (DET) or DET-35 enhances the antitumor activity of vemurafenib against both vemurafenib sensitive and resistant melanoma cells." (PMID 40617808, 2025). "Furthermore, it has been demonstrated that in melanoma, BET inhibitors enhance GPX4 inhibition-induced ferroptosis through dual downregulation of AKR1C2." (PMID 40531841, 2025). "The protein levels of SLC7A11 and GPX4 were downregulated by 6-MF, IFN-γ or their combination in A375 and B16-F10 melanoma cells, indicating that ferroptosis might be induced in the presence of these therapeutic strategies." (PMID 41347180, 2025). "For example, inhibition of GPX4 or acyl-CoA synthetase long-chain family member 4 (ACSL4), a key enzyme that promotes lipid peroxidation, significantly enhances the efficacy of ICIs in melanoma models." (PMID 40376583, 2025). "The indirect NTP treatment did not have an effect on the expression of GPX4 in either of the melanoma cell lines." (PMID 39349444, 2024). "DET and DETD-35 trigger ferroptosis in PLX4032-sensitive (A375) and PLX4032-resistant (A375-R) BRAFV600E melanoma cells through inhibiting GPX4 via non-covalent binding." (PMID 37795022, 2023). "Melanoma that metastasizes through the blood rather than the lymphatic system became dependent on the ferroptosis inhibitor GPX4." (PMID 37996827, 2023). "Moreover, dependency on GPX4 exists across diverse therapy-resistant states characterized by high expression of ZEB1, such as TGFβ-mediated therapy resistance in melanoma." (PMID 37024452, 2023). "For example, relative to primary cutaneous tumors, metastasizing melanoma cells exhibit increased dependence upon the folate pathway, monocarboxylate transporter-1 (MCT1), and glutathione peroxidase-4 (GPX4), each of which directly or indirectly attenuate oxidative stress." (PMID 35110412, 2022). "A non-genetic addiction to GPX4 accompanied drug-resistant patient-derived melanoma cells reliant on transforming growth factor beta (TGF-β)." (PMID 32340261, 2020). "In contrast, GPx4 over expression and NAC did protect melanoma cells from TPP-mediated cytotoxicity, suggesting a significant role for lipid peroxidation with the formation of lipid hydroperoxides and aldehydes in TPP toxicity, leading to thiol mediated oxidative stress." (PMID 33378390, 2020). "Inhibition of GPX4 with the compound RSL3 has been shown to selectively reduce the population of persistent cancer cells in various cancer cell lines, including breast (BT474), melanoma (A375), ovarian (Kuramochi), and lung (PC9), and as well as in A375 melanoma xenograft models." (PMID 41404065, 2025). "GPX4 inhibitor RSL3 selectively reduced the residual persistent cell pool in several types of cancer cell lines including melanoma (A375 cell line), breast (BT474 cell line), lung (PC9 cell line) and ovarian (Kuramochi) cancer cells as well as in A375 melanoma cell lines-derived xenograft models." (PMID 34135460, 2021). "In addition, GPX4 knockout was lethal in chemoresistant, but not drug-naive, A375 melanoma cells, while this could be prevented by chemical inhibitors of ferroptosis such as ferrostatin-1." (PMID 32340261, 2020). "In the case of melanoma, the compound TPL@TFBF, which does not rely on GPX4, induces tumor cell ferroptosis through the NRF2 pathway, thereby promoting immune responses and inhibiting tumor proliferation and metastasis." (PMID 38853203, 2024).
glioblastoma (68 papers, 2020 to 2025). The most malignant astrocytic tumor (WHO grade IV). "Ferroptosis can also be thwarted on other levels of the ferroptosis–inducing process, for example by selenium–mediated inhibition of the antioxidant glutathione peroxidase 4 (GPx4), which is also implicated in the pathophysiology of glioblastoma (7, 69, 70b)." (PMID 34926298, 2021). "Experiments showed that activation of the NF-κB pathway also plays a significant role in the incidence of glioblastoma ferroptosis, and that merely knocking out the GPX4 gene was insufficient to cause effective ferroptosis in cancer cells in some tumors, such as glioblastoma." (PMID 40969276, 2025). "ML210 demonstrates significant antitumor efficacy in preclinical models by efficiently penetrating the blood–brain barrier (BBB), selectively inhibiting GPX4 and inducing ferroptosis in glioblastoma, resulting in a 50% reduction in tumor volume." (PMID 40427071, 2025). "For instance, curcumin analogs promote androgen receptor (AR) ubiquitination, disrupting GPX4-mediated redox homeostasis and inhibiting temozolomide-resistant glioblastoma growth." (PMID 39935430, 2025). "Qianxue Chen and colleagues, through transcriptomic sequencing, in vivo and in vitro experiments, found that the SREBP‐specific inhibitor fatostatin induces ferroptosis in glioblastoma by inhibiting the AKT/mTORC1/GPX4 signaling pathway." (PMID 40145543, 2025). "An increase in the mRNA expression of SOD2, GSR, and GPX4 was observed only in the MDR glioblastoma cell line, while CAT mRNA expression levels remained unchanged upon treatment with 2 and 5 in both cell lines." (PMID 41471777, 2025). "Ferroptosis happens in glioblastoma when the NF-κB pathway is triggered while the GPX4 gene is silenced." (PMID 40969276, 2025). "METTL3-mediated m6A methylation of GPX4 prevents ferroptosis in Glioblastoma cells and ultimately promoting tumor progression." (PMID 40175350, 2025). "Chen et al22 suggested that treatment with ALZ003, a curcumin analog, reduced ROS accumulation, lipid peroxidation, and GPX4 expression in glioblastoma cells, suggesting the presence of ALZ003-induced ferroptosis." (PMID 39150386, 2024). "In summary, our study provided evidences that FOXP3 facilitates the progression of glioblastoma by inhibiting ferroptosis via the linc00857/miR-1290/GPX4 axis, highlighting FOXP3 as a potential therapeutic target for GBM." (PMID 38561331, 2024). "The synergy of three actions, dihydroorotic dehydrogenase catabolism, glutathione peroxidase 4 iron death defense axis and Fe2+ release mediated by Fe3O4 nanoparticles, promotes iron death in glioblastoma." (PMID 38173021, 2024). "EVs modified with Angiopep-2 peptides are loaded with iron nanoparticles, glutathione peroxidase 4 and dihydroorotic dehydrogenase inhibitors to target glioblastoma by local magnetic localization and lipoprotein receptor protein 1 recognition." (PMID 38173021, 2024). "For example, studies have demonstrated the selective killing effect of dihydroartemisinin on glioblastoma via GPX4 inhibition, suggesting a novel treatment direction." (PMID 39724413, 2024). "In our study, through transcriptome sequencing, in vivo experiments, and in vitro experiments, we found that fatostatin induces ferroptosis by inhibiting the AKT/mTORC1/GPX4 signaling pathway in glioblastoma." (PMID 36966152, 2023). "In our study, we found that the positive expression of SLC7A11 and GPX4, which reduce phospholipid hydroperoxide and prevent ferroptosis, was decreased in U251 glioblastoma cells." (PMID 37582760, 2023). "Remarkably, another research report found that ALZ003, another curcumin analog, also reduced GPX4 expression in glioblastoma cells." (PMID 36814470, 2023). "Previous studies have shown that GPX4 promotes the growth of glioblastomas as well as the migration and invasion potential of gastric and renal cancers." (PMID 38134213, 2023).
glioblastoma (continued). "Dihydroartemisinin can act as an inhibitor of GPX4 and system Xc-, increasing the accumulation of lipid peroxides in glioblastoma cells and inducing ferroptosis." (PMID 36910646, 2023). "Activated NF-κB inhibits ferroptosis in granulosa cells of polycystic ovary syndrome by upregulating the expression of GPX4, but which induces ferroptosis in glioblastoma by repression of SLC7A11." (PMID 37153794, 2023). "In the study of glioblastoma, RSL3 inhibits the activity of GPX4, drives the occurrence of ferrozois and induces oxidative death of glioblastoma cells, providing new therapeutic ideas for glioblastoma." (PMID 36937839, 2023). "Recent data associated RSL3 activity with the activation of the NF-kB pathway and the depletion of GPX4, which induced lipid peroxidation in glioblastoma cells, reducing proliferation." (PMID 35805884, 2022). "For instance, a recent study developed a combinatorial therapy for glioblastoma based on iron oxide NPs (IONPs) co-loaded with siRNAs-targeting glutathione peroxidase 4 (si-GPX4) and cisplatin (Cs, platinum-based anticancer drug)." (PMID 36358663, 2022). "RSL3-induced ferroptosis in glioblastoma cells was characterized by an increase in lipid ROS and a decrease in GPX4, ATF4, and xCT expression." (PMID 34987700, 2021). "Through the determination of ferroptosis-related protein expression, we found that the significant decrease of GPX4, accompanied by the constant expression of xCT and ACSL4, suggesting GPX4 was a pivotal target for DHA-activated ferroptosis in glioblastoma." (PMID 32452511, 2020). "Similarly, albumin-bound paclitaxel sensitizes glioblastoma cells to temozolomide by downregulating GPX4 and impairing DNA damage repair." (PMID 39935430, 2025). "RAS-selective lethal 3 (RSL3), a well-known inhibitor of glutathione peroxidase 4 (GPX4), could effectively induce oxidative cell death in glioblastoma cells through ferroptosis." (PMID 40969276, 2025). "In glioblastoma, Selenoprotein P maintains GPX4 levels, contributing to chemoresistance." (PMID 39935430, 2025). "Specifically, the study aimed to evaluate whether boric acid treatment in U87 glioblastoma cells could serve as a potential therapeutic strategy for glioblastoma by targeting the SOX10/GPx4/ACSL4 signalling axis." (PMID 40159622, 2025). "Similarly, dihydroartemisinin increased TfR expression and downregulated GPX4 in U87 and A172 glioblastoma cell lines, although the expression levels of other proteins involved in the ferroptotic process were not affected." (PMID 37132605, 2024). "In glioblastoma, inhibition of GPX4 expression by RSL3 induces ferroptosis." (PMID 37978473, 2023). "In addition, RAS-selective lethal 3 (RSL3), an inhibitor of GPX4, bonds with GPX4, which effectively leads to lipid peroxides and downregulates ion GPX4 in glioblastoma, resulting in ferroptosis of glioblastoma." (PMID 37458878, 2023). "To investigate whether SLC7A11 and GPX4 inhibit NeuroD4-mediated neuronal reprogramming in glioblastoma cells, we co-overexpressed SLC7A11 and GPX4 along with NeuroD4." (PMID 37582760, 2023). "GPx4 inhibition leads to the imbalance of oxidative defenses and an increase in oxidative stress that consequently leads to ferroptosis; thus, inhibitors of GPx4 pathway can be exploited against highly aggressive forms of cancer such as glioblastoma, one of the most malignant brain tumors." (PMID 38139106, 2023). "Nrf2 can regulate the expression of GPX4 and Xc- in glioblastoma." (PMID 35252001, 2022). "Nevertheless, up to now, the evidence regarding how these GPX4-independent pathways act in glioblastoma and how they can be modulated to improve the current treatments remains unclear, indicating the need for further investigation in this field." (PMID 35805884, 2022).
glioblastoma (continued). "Assuming that the inhibition of GPX4 leads to the accumulation of lipid peroxides, which in turn cause damage to cellular lipid membranes, inducing ferroptosis, the modulation of GPX4 is a potential therapeutic strategy against many cancer types including glioblastoma." (PMID 35805884, 2022). "Furthermore, RNAi-mediated GPX4 silencing cannot trigger ferroptosis in glioblastoma cells unless the NF-κB pathway is activated simultaneously." (PMID 34987700, 2021). "RSL3, an inhibitor of GPX4, has been reported to induce ferroptosis in various cancers such as glioblastoma; however, the underlying mechanism is not yet fully understood." (PMID 34987700, 2021). "In addition, we observed that activation of the NF-κB pathway combined with GPX4 depletion contributed to ferroptosis in glioblastoma cells." (PMID 34987700, 2021). "To verify whether GPX4 depletion alone would result in ferroptosis, we silenced GPX4 expression and examined the viability of glioblastoma cells." (PMID 34987700, 2021). "Indeed, GPX4 expression was dramatically decreased after ALZ003 treatment in the dose-dependent manner in TMZ-sensitive and –resistant glioblastoma, suggesting that ALZ003-mediated ROS accumulation is caused by the downregulation of GPX4." (PMID 31896509, 2020). "These suggested that DHA activated ferroptosis by the inhibition of GPX4 in glioblastoma." (PMID 32452511, 2020). "Indeed, treatment with RSL3, a GPX4 inhibitor, induces ferroptosis in glioblastoma cells." (PMID 39408223, 2024). "Notably, the mRNA expression of GPX4, which provides protection against overoxidation and prevents cells from undergoing ferroptosis, exhibited a significant decrease in NeuroD4-overexpressing glioblastoma cells." (PMID 37582760, 2023). "The expression of ibuprofen may inhibit the activity of GPX4 and Xc- by down-regulating the expression of Nrf2, which increases the production of lipid ROS in tumor cells, which in turn promotes the occurrence of ferroptosis in glioblastoma." (PMID 35252001, 2022). "Furthermore, we found that decreased ATF4 and xCT expression in RSL3-treated cells could be prevented by NF-κB pathway inhibition, and NF-κB pathway activation in GPX4-depleted glioblastoma cells reduced ATF4 and xCT expression." (PMID 34987700, 2021). "In glioblastoma, capsaicin induces redox imbalance and ferroptosis in U87-MG and U251 cells primarily via the ACSL4/GPX4 signaling pathway." (PMID 40994946, 2025). "It has been also described that NF-κB activation in glioblastoma cells by RSL3 treatment leads to an increase of lipid ROS and a reduction of anti-ferroptosis proteins such as GPX4, ATF4, and SLC7A11." (PMID 38539832, 2024). "In conclusion, our study demonstrated that GDEs induce lipid accumulation in DCs infiltrating glioblastoma, and leading to ferroptosis in mDCs through the NRF2/GPX4 signaling pathway." (PMID 39192971, 2024). "In glioblastoma cells, NF-κB activated by RSL3 increases lipid ROS and decreases GPX4, activating transcription factor 4 (ATF4) and SLC7A11; NF-κB combined with GPX4 depletion induces ferroptosis." (PMID 39595619, 2024). "However, RSL3, an inhibitor of GPX4, could severely hinder glioblastoma cell proliferation." (PMID 34987700, 2021). "We found that RSL3 led to an increase in lipid ROS concentration and downregulation of ferroptosis-related proteins such as GPX4, ATF4, and SLC7A11 (xCT) in glioblastoma cells." (PMID 34987700, 2021). "ATF4 and xCT protein levels remained the same in GPX4-depleted cells, but their expression was downregulated in RSL3-treated glioblastoma cells." (PMID 34987700, 2021). "The expression level of SLC7A11 in biopsy tissues and glioma cell lines of patients with glioblastoma was higher than that in normal brain tissues; therefore, inhibition of system XC- or the GPx4 system by a FIN can enhance the RT effect in sarcoma, breast cancer and glioblastoma." (PMID 37007068, 2023).